COL1A2 (collagen type I alpha 2 chain)
Diseases named in the same sentence as COL1A2 in open-access papers (continued):
Sharing a sentence is not in itself a finding about the gene and the disease.
melanoma (31 papers, 2009 to 2025). A malignant, usually aggressive tumor composed of atypical, neoplastic melanocytes. "On one hand, frequent promoter methylation of COL1A1 has been observed in renal cell carcinoma and hepatocellular carcinoma, and COL1A2 downregulation has been reported in melanoma, head and neck cancer, and bladder cancer." (PMID 41463322, 2025). "COL1A2 is also a fibroblast-specific promoter that affects melanoma angiogenesis and metastasis via the influention of the connective tissue growth factor (CCN2)/CAF pathway." (PMID 37762054, 2023). "As subset of the stromal collagen gene, COL1A2 is considered to be a potential molecule marker of melanoma, as it is frequently affected by melanoma methylation." (PMID 37762054, 2023). "Intriguingly, mRNA levels of COL1A1 and COL1A2, coding for collagen type 1, which is most abundant of the collagens, were also linked with PTGES in patients with melanoma." (PMID 37529399, 2023). "In contrast, COL1A2 was significantly downregulated in bladder cancer, malignant melanoma and head and neck cancer." (PMID 36171259, 2022). "COL1A2 was downregulated in many cancers, including melanoma, bladder cancer, and head and neck cancer." (PMID 31612481, 2020). "For example, Koga showed hypermethylation and limited expression of COL1A2 in melanoma by using NimbleGen C4226-00-01promoter-tiling arrays and 2005-04-20_Human_60mer_1in2 genome wide human expression arrays." (PMID 30719424, 2018). "It identified 76 differentially methylated markers, most of which—89% (68/76), were hypermethylated, and only a minority was previously reported in melanoma at the time (COL1A2, RAB33A, DDIT4L, and HOXB13)." (PMID 28396701, 2017). "On one hand, frequent promoter methylation of COL1A1 was detected in renal cell carcinoma and hepatocellular carcinoma, and COL1A2 was downregulated in melanoma, head and neck cancer, and bladder cancer." (PMID 27894325, 2016). "Expression of COL1A2 is frequently silenced by hypermethylation of its promoter in colorectal cancer, cancer cell lines and in melanoma, suggesting a potential role as a tumor suppressor." (PMID 27519597, 2016). "Based on the literature, hypermethylation of COL1A2 was confirmed in head and neck cancer, melanoma, and bladder cancer." (PMID 26482433, 2015). "COL1A2 gene expression was epigenetically down-regulated in medulloblastoma, melanoma, head and neck cancer, and bladder cancer." (PMID 24552139, 2014). "Downregulation of these genes by CtBP1 was confirmed by transient transfection of CtBP1 into the melanoma cell line (Col1A2: 0.31, FAT: 0.52, SLC26A2: 0.72, VCAN: 0.75 compared to mock control set as 1)." (PMID 19216735, 2009). "To examine the role of Col1A2-Cre-CAF–specific Ccn1 expression in melanoma metastasis, we used mice expressing a tamoxifen-dependent Cre recombinase expressed under the control of a fibroblast-specific promoter/enhancer that was derived from the human COL1A2 gene." (PMID 38363129, 2024). "However, COL1A1 and COL1A2 were both strongly overexpressed in the melanomas compared to melanocytomas, in agreement with the study from Van Kempen." (PMID 28743863, 2017). "Among the CpG loci exhibiting hypermethylation in melanomas, FRZB_P406_F and COL1A2_E299_F were relatively unmethylated in nevi, having mean β-values near 0.1, but showed considerably higher methylation in many melanomas, with mean β-values between 0.6 and 0.7." (PMID 21375697, 2011). "The 12 CpG loci identified by PAM analysis that provided the most accurate prediction of melanoma were RUNX3_P393_R, RUNX3_P247_F, RUNX3_E27_R, COL1A2_E299_F, MPO_P883_R, TNFSF8_E258_R, CD2_P68_F, EVI2A_P94_R, OSM_P188_F, ITK_P114_F, FRZB_P406_F, and ITK_E166_R." (PMID 21375697, 2011).
melanoma (continued). "Interestingly, the silencing of COL1A2 via methylation is common in melanoma cell lines and tumors, suggesting that paclitaxel treatment could induce cell changes that are also present in cancerous cells." (PMID 37627219, 2023). "A smaller tissue from patient ID 9561, collected in 2008, had four clusters, including melanoma (PMEL, TYRP1), immune cells (TMSB4X, IL32), keratinocytes (KRT10, KRT1, DSG1), and fibroblast areas (COL1A2, COL1A1, DCN)." (PMID 39846232, 2025). "Promoters of COL1A2, HSPB6, NPM2, MT1G or DDIT4L were identified as hypermethylated in melanoma cells suggesting that they can be used as predictors for melanoma progression." (PMID 40427015, 2025). "We confirm previous reports that COL1A2, THBS1, TNFRSF10D and UCHL1 are highly methylated in melanoma, thus providing further evidence that these genes are highly important in melanocytic neoplasia." (PMID 22028813, 2011). "Summary of COL1A2, THBS1, TNFRSF10D and UCHL1 methylation in melanocytes, melanoma cell lines, fresh-frozen melanoma tumors and other cancer cell lines." (PMID 22028813, 2011). "On average, the COL1A2 and TNFRSF10D promoters appeared >10–fold more methylated in melanoma cell lines compared to melanocytes, and 6-fold higher in the fresh tumors." (PMID 22028813, 2011). "We defined clusters corresponding to melanoma (PMEL, MLANA), immune infiltrates (TRBC2, TRAC, TMSB4X), melanophages (CD74, LYZ), keratinocytes (KRT14, TRIM29), blood vessels (CAVIN1, PECAM), and fibroblast‐enriched areas in the dermis (DCN, COL1A2, FBLN1)." (PMID 39846232, 2025). "Interestingly, our analysis of COL1A2 and GPX3—previously reported to be hypermethylated in melanoma—in the four patient-derived sets of melanoma and melanocytes showed completely different results." (PMID 30719424, 2018). "The results were validated by bisulfite sequencing of COL1A2, NPM2, HSPB6, DDIT4L, and MT1G promoters, which exhibited increasing incidence with advanced melanoma stage, suggesting potential use as predictors of melanoma progression." (PMID 28396701, 2017). "Over fifty percent (21/40) of the melanoma cell lines had no COL1A2 mRNA expression, which correlated with a high degree of COL1A2 promoter methylation in 67% of this subset." (PMID 22028813, 2011). "Finally, we identify the importance of Col1A2-Cre-fibroblast (i.e., universal fibroblast) expression of Ccn1 in coordinating these activities, emphasizing the importance of the CAF in the phenotype and development of cancers, including melanoma." (PMID 38363129, 2024).
colorectal cancer (26 papers, 2011 to 2024). A primary or metastatic malignant neoplasm that affects the colon or rectum. "Collectively all these experimental data clearly reveal that the COL11A1 gene along with its associated THBS2, COL10A1, COL5A2, and COL1A2 might serve as a prognostic biomarker for colorectal cancer." (PMID 33597969, 2021). "Another study identified COL1A2 as a core gene for colorectal cancer and it played important roles in tumor progression and prognosis of stage IIA colon cancer." (PMID 37805556, 2023). "It has been found that low expression of miR-4728-3p in ulcerative colitis-associated colorectal cancer can influence CAV1, THBS2, and COL1A2 genes as well as focal adhesion signaling, which is related to tumor pathogenesis." (PMID 35733095, 2022). "Low expression of LGALS4 is associated with poor survival rate, while high expression of COL1A2 and the new reported gene DARS is linked to poor survival rate in colorectal cancer patients." (PMID 34249670, 2021). "Collectively all these results reveal that the COL11A1 gene has a positive association and correlation with THBS2, COL10A1, COL5A2, and COL1A2 to upregulate the gene expression to induce the development of colorectal cancer." (PMID 33597969, 2021). "In colorectal cancer, COL1A2 has been found to play a role in tumor invasion and metastasis." (PMID 38913913, 2024). "The PathwayMapper tab in cBioPortal servers shows the alteration frequency of COL11A1, THBS2, COL10A1, COL5A2, and COL1A2 over the various pathways on the colorectal cancer dataset using a white to red color scale where the more frequently altering gene shows greater intensity of the red color." (PMID 33597969, 2021). "Upregulation of COL1A2 was reported in blood and tumor tissues of patients with colorectal cancer." (PMID 31612481, 2020). "Another study demonstrated that COL1A2 may affect proliferation, migration, and invasion of colorectal cancer cells." (PMID 33193601, 2020). "Inhibition of COL1A2 expression in colorectal cancer cell could suppress cell proliferation and invasion." (PMID 31612481, 2020). "On the other hand, COL1A1 and COL1A2 mRNA was upregulated in colorectal cancer and medulloblastoma." (PMID 27894325, 2016). "A previous study showed that expression of COL1A1 and COL1A2 was elevated in malignant colorectal endothelium cells, suggesting that these two proteins play a role in angiogenesis and formation of desmoplasia during colorectal cancer development." (PMID 25860484, 2015). "Similarly, COL1A2 was believed to be significantly overexpressed in colorectal cancer tissues and blood samples, but the specific mechanism remains unclear." (PMID 36171259, 2022). "Although no mutations of COL1A2 have previously been reported for lymphomas, a potential pathogenetic role of these mutations is indicated from the finding that it is frequently epigenetically silenced in medulloblastoma and colorectal cancer." (PMID 32316399, 2020). "In this study, we explored that the relative expression of the Col1a2, ITIH4, MMP7, and MSX2 are increased in the mice who induced colorectal cancer (the COL group) compared with the Normal group." (PMID 38637796, 2024). "The gene profiles (Col1a2, ITIH4, MMP7, and MSX2) were identified as critical markers in colorectal cancer." (PMID 38637796, 2024). "Numerous cancers, including colorectal cancer and medulloblastoma, have higher expression levels of COL1A1 and COL1A2." (PMID 37396945, 2023). "Growing evidence has indicated that the genes of Col1a2, ITIH4, MMP7, and MSX2 profiles could be critical markers for identifying colorectal cancer." (PMID 38637796, 2024).
colorectal cancer (continued). "The PPI networks indicate the RAB31, COL1A1, COL1A2, COL3A1, COL11A1, and VCAN as the most important protein network that likely to be connected and show betweenness among themselves to significantly promote the prognosis of colorectal cancer." (PMID 33597969, 2021). "CircFMN2/miR-1182 may also regulate the progression of colorectal cancer by targeting CD44, GNG7, RB1, COL1A2, PLCB1, SLC17A7, and TERT." (PMID 34249673, 2021).
lung fibrosis (25 papers, 2009 to 2025). "However, deficient autophagy in this model enhanced lung fibrosis, which was characterized by upregulation of collagens, COL1A2 and COL3A1." (PMID 28424691, 2017). "Consistently, Piezo1 deletion with Col1a2-CreERT2, a cre line mainly targeting fibroblast-traced myofibroblasts, also moderately attenuated bleomycin-induced lung fibrosis." (PMID 40454481, 2025). "Similar to the results in lung fibrosis, expression of Col1a1, Col1a2, and Acta2 was inhibited in MHP1-AcN-treated mice." (PMID 35864207, 2022). "Marked lung fibrosis, as evidenced by increased picrosirius red staining area and elevated hydroxyproline content, was established both in control and Col1a2-Cre/ERT2*Txndc5fl/f mice 7 days after BLM treatment." (PMID 32848143, 2020). "To determine the in vivo contribution of fibroblast TXNDC5 to pulmonary fibrosis, we generated a mouse line with inducible, fibroblast-specific Txndc5 deletion (Col1a2-Cre/ERT2*Txndc5fl/fl, abbreviated as Txndc5cKO)." (PMID 32848143, 2020). "In contrast, tamoxifen-injected Bosutinib-treated TBRIca-Col1a2-Cre mice displayed a dose-dependent decrease in pulmonary fibrosis and alveolar/parenchymal abnormalities compared with animals injected with tamoxifen alone." (PMID 29718973, 2018). "These mice, carrying a floxed constitutively active TGF-β receptor (TBRI) allele activated by tamoxifen-induced Cre recombinase expression under control of the fibroblast-specific Col1A2 promoter develop extensive cutaneous and lung fibrosis." (PMID 29718973, 2018). "To further implicate EGFR upregulation in lung fibrosis we investigated the mRNA expression levels of type I collagen (COL1A2) in different types of IIPs." (PMID 23841084, 2013). "First, we showed that PF543 administered following bleomycin exposure reduces lung expression of markers indicative of ongoing pulmonary fibrosis by activated fibroblasts such as fibronectin, Col1A2, and α-SMA in a manner that parallels our histologic findings." (PMID 32764262, 2020). "Moreover, BLM-induced lung fibrosis in WT mice was significantly reduced in myeloid cell TERT-deficient mice as manifested by several markers of fibrosis, including α-SMA (Acta2), type I collagen (col1a2), and TGFβ (Tgfb)." (PMID 36045668, 2022). "Like bleomycin challenged Ppp1r15a−/− mice, wt mice treated with Sephin1 had significantly increased lung fibrosis at day 21 compared with the vehicle control treated mouse group, as measured by lung tissue hydroxyproline, and whole lung gene expression of Col1a2." (PMID 34732748, 2021). "Collagen I has a triple helix structure that arises from two α-1 and one α-2 chains, which are the products of the COL1A1 and COL1A2 genes, respectively; down-regulation of COL1A1 alleviates the accumulation of ECM and then inhibits pulmonary fibrosis." (PMID 37794454, 2023). "In pulmonary fibrosis, MRTF-A interacts with the serum response factor (SRF) in the nuclear matrix and promotes transcription of COL1A2 and TGF-β1, which increases the stiffness of ECM." (PMID 35250619, 2022). "In contrast, we find an enrichment of several markers of pulmonary fibrosis (CLU, COL1A1, COL1A2, and COL3A1) in SARS-CoV-2-low patients (these correspond to the later stages of infection), indicating that there are two distinct stages of infection." (PMID 35233546, 2022). "Col1a1, Col1a2, and α-SMA are considered the main pulmonary fibrosis markers, and their levels reflect the degree of pulmonary fibrosis." (PMID 36182915, 2022). "We speculate that, under normal conditions, AnxA2 is involved in physiological COL1A2 regulation to prevent excessive deposition of type I collagen which is characteristic of many fibrotic disorders such as systemic sclerosis, hepatic cirrhosis and pulmonary fibrosis [Varga and Jimenez, 1995]." (PMID 25290763, 2015). "The increased transcripts of col1a2 and col3a1 and protein level of α-SMA showed that the lung fibrosis aggravated after BLM treatment and peaked around the 3rd week." (PMID 23476100, 2013).
lung fibrosis (continued). "Increased levels of lysyl oxidase (LOX), an amine oxidase critical for the initiation of collagen and elastin cross-linking, increased mRNA levels of collagen type I (Col1a2), collagen type III (Col3a1) and matrix metalloproteinase (Mmp2) have been reported in murine models of lung fibrosis." (PMID 24204629, 2013). "Additionally, since Axl was also expressed in fibroblast and may promote their activation, we used Col1a2‐Cre::Axlfl/fl mice to confirm the effects of Axl deletion in fibroblast and myofibroblasts on BLM‐induced pulmonary fibrosis." (PMID 39779468, 2025). "Similarly, we find enrichment of several markers of pulmonary fibrosis (CLU, COL1A1, COL1A2, and COL3A1) in SARS-CoV-2-low samples as compared with nonviral and viral ARDS samples, exemplifying the profound lung injury and fibrosis during later stages of COVID-19." (PMID 35233546, 2022). "Similarly, MPs isolated from SSc patients with lung fibrosis showed a greater profibrotic profile, with an upward trend for Col1a1/MMP1 (median of 1.59 vs. 0.65, p=0.1) and Col1a2/MMP1 ratio (median of 2.42 vs. 0.91, p=0.07), but reduced ability to induce CCL2 (median of 0.89 vs. 1.51, p<0.05)." (PMID 33193304, 2020).
ovarian carcinoma (24 papers, 2015 to 2024). A malignant neoplasm originating from the surface ovarian epithelium. "Increased expressions of COL1A1 and COL1A2 genes were associated with lower survival of ovarian cancer patients." (PMID 32315343, 2020). "In ovarian cancer, overexpression of COL1A2 has been associated with resistance to several chemotherapies by decreasing apoptosis." (PMID 32525891, 2020). "GREB1 overexpression in ovarian cancer cell lines increased cell proliferation and migration and promoted a mesenchymal morphology associated with increased Col1a2, which encodes a collagen I subunit." (PMID 29973689, 2018). "The expression of COL3A1, COL5A2, and COL1A2 was also studied by immunocytochemistry and western blot analysis and found to be associated to drug-resistance in ovarian cancer." (PMID 28562334, 2017). "In ovarian cancer, COL1A2 has been associated with tumor cell proliferation and migration." (PMID 38913913, 2024). "Moreover, COL3A1, COL5A2 and COL1A2 expression are associated with drug-resistance in ovarian cancer." (PMID 31533654, 2019). "Through further analysis of these key genes and cancer stem cell subpopulation, more critical genes can be obtained as LCP2, FCGR3A, COL1A1, COL1A2, MT-CYB, CCT5, and PAPPA, are closely associated with ovarian cancer." (PMID 35360863, 2022). "And COL1A2 plays an important role in the invasion and metastasis of ovarian cancer cells since it promotes the migration of cancer cells by interacting with α2β1-integrin." (PMID 33543230, 2021). "The best of our knowledge this research for the first time describes the expression of COL1A2 in ovarian cancer cells of the tumor." (PMID 30583585, 2018). "Col1a2 differential transcription is associated with an EMT in a variety of cell types, representing both fibrosis and cancer models, including ovarian cancer." (PMID 29973689, 2018). "For the COL1A2 all ovarian cancer subtypes expressed the protein, with moderate expression in serous carcinoma and strong in mucinous and endometriod carcinoma." (PMID 30583585, 2018). "Expression profiles of COL2A1 and COL1A2 were independent predictors of survival in ovarian cancer and head and neck cancer respectively." (PMID 28410203, 2017). "From this module, COL16A1, COL3A1, and COL1A2 are likely to be ovarian cancer genes, as they are cancer genes and are enriched with at least one pathway containing ovarian cancer genes." (PMID 25611546, 2015). "In addition, transcriptomic analysis of the TCGA-ovarian cancer dataset revealed a positive correlation of ITGA2 expression to COL1A2, COL3A1, and COL5A1 involved in focal adhesion pathway." (PMID 33026975, 2020). "COL1A1 and COL1A2 may be involved in the occurrence and metastasis of ovarian cancer." (PMID 35360863, 2022). "However, in pancreatic and ovarian cancer, COL1A2 was upregulated." (PMID 31612481, 2020). "Through the analysis of stemness-related key genes and tumor stem cell subpopulations, LCP2, FCGR3A, COL1A1, COL1A2, MT-CYB, CCT5, and PAPPA are closely related to ovarian cancer." (PMID 35360863, 2022). "COL1A2 is a component of the extracellular matrix (ECM), but is also observed in many breast and ovarian cancer drug-resistant cell lines, which indicates that it can play an important role in drug resistance at the tissue and cellular level." (PMID 32525891, 2020). "From the total of 34 ligand and receptor genes identified in these interactions, seven (COL1A1, ITGB5, COL1A2, FGFR2, FN1, IGF1, and IGF2) were consistently up-regulated and predicted worse overall survival in two additional cohorts (TCGA and GSE9891) of ovarian cancer patients." (PMID 36352420, 2022). "In our new analytical process, the key genes related to ovarian cancer are identified as LCP2, FCGR3A, COL1A1, COL1A2, MT-CYB, CCT5, and PAPPA, which may have important significance in ovarian cancaer and drug therapy." (PMID 35360863, 2022).